INS (insulin)
Diseases named in the same sentence as INS in open-access papers (continued):
Sharing a sentence is not in itself a finding about the gene and the disease.
type 2 diabetes (continued). "In adulthood, studies have shown low birth weight to be associated with higher blood pressure, lower insulin sensitivity and increased incidence of type 2 diabetes mellitus, greater cardiovascular disease risk, and increased mortality." (PMID 25760717, 2015). "Obesity increases the risk of cardiovascular disease and type 2 diabetes, partly through reduced insulin-induced microvascular vasodilation, which causes impairment of glucose delivery and uptake." (PMID 26003324, 2015). "With increases in type 2 diabetes and cancer associated with deregulated insulin signalling, there is substantial interest in therapeutically manipulating insulin-signalling pathways." (PMID 25808059, 2015). "The type 2 diabetes risk G-allele of FAF1-rs17106184 associated with increased levels of 2-hour serum insulin (n=5,547, β=0.055, p=0.017) in Inter99 and also when combining effects with three additional Danish studies (n=6,260, β=0.062, p=0.0040)." (PMID 25799151, 2015). "This in turn stimulates the secretion of insulin by pancreas and increases susceptibility to developing type II diabetes." (PMID 25797421, 2015). "The insulin circuit has been implicated in type II diabetes, a complex genetic disease and serious public health risk." (PMID 25774510, 2015). "Alterations and/or variations in the activity of ZnT8 is associated with impaired glucose induced insulin response, which promotes progression from glucose intolerance to type-2 diabetes in susceptible individuals." (PMID 26381880, 2015). "This process causes an increase in plasma glucose and insulin concentrations until ß-cell failure occurs and the condition of glucose tolerance gives way to frank type 2 diabetes." (PMID 27123439, 2015). "It has been reported this gene is involved in the regulation of second-phase insulin secretion and its polymorphism contributes to an increased risk of the development of type 2 diabetes." (PMID 26018652, 2015). "Metabolic syndrome (MetS) is a multi-component disorder characterized by abdominal obesity, dyslipidaemia, hypertension and impaired insulin sensitivity, and it is associated with an increased risk of type 2 diabetes (T2DM) and cardiovascular diseases (CVD)." (PMID 26152126, 2015). "In support, similar scale increases in circulating GLP-1 in response to OGTT were associated with restoration of first-phase insulin response to IVGTT in severely obese type 2 diabetes patients undergoing bariatric surgery." (PMID 25811109, 2015). "In conclusion, our study demonstrated that serum 25-OHD is associated with insulin sensitivity and β-cell function for female newly diagnosed type 2 diabetes patients; the association is ambiguous in males." (PMID 25741510, 2015). "This marker was found associated with type 2 diabetes, serum insulin levels, β-cell function, and glucose tolerance." (PMID 25648962, 2015). "It is well known that type 2 diabetes mellitus is a chronic disease caused by pancreatic beta cells dysfunction and insulin resistance in peripheral muscle tissues." (PMID 26713097, 2015). "A major cause of type 2 diabetes is impaired insulin action in adipose tissue (AT), skeletal muscle, and the liver coupled with insufficient secretion of insulin to overcome this resistance." (PMID 25918733, 2015). "Since microglia are implicated in cascades causing neuronal loss and cognitive decline in Alzheimer’s disease (AD), insulin–AGEs formation, especially in type 2 diabetes, are most probably involved in AD that is proposed as type 3 diabetes." (PMID 26311627, 2015). "The relationships reflected the fact that GDM and type 2 diabetes shared a similar pathophysiology, characterized by deficiency in islet β cell secretion and insulin sensitivity." (PMID 26405461, 2015). "In conclusion, serum 25-OHD is associated with insulin sensitivity and β-cell function for female newly diagnosed type 2 diabetes patients, and the association is ambiguous in males." (PMID 25741510, 2015).
type 2 diabetes (continued). "In humans, PTEN haploinsufficiency was shown to have divergent effects, as they increase the risk of obesity, while decreasing that of type 2 diabetes by markedly improving insulin sensitivity." (PMID 25688211, 2015). "Type-2 diabetes (T2-D) is a chronic disease of carbohydrate metabolism caused by a deficiency in insulin secretion or ineffective insulin action." (PMID 25884658, 2015). "This study examined changes in clinical measures and associated costs for veterans with type 2 diabetes on insulin therapy converted from insulin glargine to insulin detemir." (PMID 26120575, 2015). "Specifically, insulin therapy, which is commonly used in type 2 diabetes, is frequently associated with hypoglycemia events and weight gain." (PMID 26230680, 2015). "Type 2 diabetes (T2D) is characterized by insulin resistance with an insulin secretory defect leading to relative insulin deficiency." (PMID 25226393, 2014). "The pathogenesis of type-2 diabetes involves progressive development in insulin resistance associated with a defect in insulin secretion, leading to overt hyperglycemia." (PMID 24991576, 2014). "Point mutations of the AC3 gene are also associated with decreased insulin release in animal models of type 2 diabetes." (PMID 25389406, 2014). "The HOMA-IR index is known to be a clinical parameter to evaluate hepatic insulin sensitivity and is useful to predict the risk of hypertension and type II diabetes in human diagnostics." (PMID 24498028, 2014). "Type 2 diabetes mellitus (T2DM) leads to an elevation in hepatic glucose production driven by insulin resistance in addition to progressive loss of insulin secretion and inappropriate elevations in glucagon concentrations." (PMID 24858947, 2014). "On the other hand, metformin therapy can improve the parameters of body composition and insulin dynamics in people who are at risk for type 2 diabetes." (PMID 25247153, 2014). "Among these studies, only one trial over 16 weeks has investigated the combined effects of calcium and vitamin D supplementation on insulin sensitivity and secretion in people at high risk of type 2 diabetes." (PMID 25299668, 2014). "It has been recognized that iron influences glucose metabolism and that iron stores are associated with insulin sensitivity, insulin secretion, and type-2 diabetes." (PMID 23708056, 2014). "Type 2 diabetes mellitus (T2DM) is caused by peripheral resistance to insulin and an inadequate secretory response by pancreatic beta cells." (PMID 24964098, 2014). "This polymorphism appears to be associated to type 2 diabetes in almost all the ethnic cohorts studies and people carrying the TT genotype of this variant showed impaired insulin release and impaired glucose tolerance." (PMID 24672805, 2014). "Recognized by insulin resistance (IR), some degrees of impairment in insulin secretion and hyperglycemia, type 2 diabetes mellitus (T2DM) is a metabolic disease that is linked to different pathophysiological mechanisms." (PMID 25202440, 2014). "Results from this study demonstrate that insulin detemir and insulin glargine caused altered feeding behaviors in a type 2 diabetes rat model." (PMID 25197671, 2014). "For instance, an increase of skeletal muscle ceramide was observed in obese men with risk for type 2 diabetes and was inversely related to insulin sensitivity." (PMID 25228885, 2014). "This predisposition to type 2 diabetes is a consequence of defects in both insulin action and insulin secretion." (PMID 25310961, 2014). "Our main result are in agreement with previous studies showing inverse association between insulin resistance and exercise capacity both in healthy subjects, relatives of patients with type 2 diabetes and in patients with type 2 diabetes." (PMID 24612649, 2014). "Type 2 diabetes is caused by a progressive decrease of insulin sensitivity and pancreatic β-cell function." (PMID 24692847, 2014).
type 2 diabetes (continued). "The main message of this study is that the patient’s glucose profile predicts risk of weight gain, which is a known problem in starting insulin treatment in type 2 diabetes patients." (PMID 23880900, 2014). "In total, 317 SNPs were identified showing associations (P<10−6) with type 1 diabetes, type 2 diabetes or related traits (glucose-, insulin- and proinsulin traits)." (PMID 25375650, 2014). "Nevertheless, IL-1 has also been implicated in the pathogenesis of type 2 diabetes as chronic inflammation contributes to the failure of β-cells to secrete sufficient amounts of insulin." (PMID 25548896, 2014). "Most findings demonstrating the association between adipose tissue dysfunction and type 2 diabetes have been shown in mouse models or subjects with manifest obesity and/or impaired insulin sensitivity." (PMID 25148116, 2014). "If we adjust for age, sex, BMI age- and sex-specific percentiles, and fasting plasma insulin levels (model 2), the K-allele-containing genotype is an independent risk factor of type 2 diabetes (odds ratio = 4.105, 95% CI: 1.0008–16.831, and P = 0.047)." (PMID 25309595, 2014). "Variants that increase the risk of type 2 diabetes influence beta-cell development and function and focus attention on insulin secretion in the development of disease." (PMID 23982303, 2014). "Studies showed the similarity of omentin and adiponectin, especially the effect on weight loss, insulin sensitivity, and type 2 diabetes (T2DM)." (PMID 24899788, 2014). "Changes in the levels of specific microRNAs (miRNAs) can reduce glucose-stimulated insulin secretion and increase beta-cell apoptosis, two causes of islet dysfunction and progression to type 2 diabetes." (PMID 23828613, 2014). "Low serum 25-hydroxyvitamin D [25(OH)D] concentrations and dietary calcium intake have been associated with impaired insulin sensitivity or secretion in people at high risk of type 2 diabetes." (PMID 25299668, 2014). "In humans, it has been proposed that increased levels of insulin in the blood is a primary cause of Type 2 diabetes associated with hypertension and cancers." (PMID 24795642, 2014). "This process is believed to contribute to the decrease of the β cell mass, leading to a deficient insulin secretion and therefore the development of Type 2 diabetes." (PMID 24586495, 2014). "25OHD level has been associated with insulin sensitivity indices, and low 25OHD has been shown to predict later development of type 2 diabetes." (PMID 25000408, 2014). "Type 2 diabetes is a chronic insufficiency in the processing of glucose in the blood caused by too little insulin being produced by the body or by the available insulin working ineffectively." (PMID 25479769, 2014). "Type 2 diabetes is a complex metabolic disease, caused by reduced insulin sensitivity and relative insulin deficiency." (PMID 25431771, 2014). "At present, many studies have reported that rs1805192 and rs3856806 polymorphisms were associated with obesity, insulin sensitivity and Type 2 diabetes." (PMID 24460649, 2014). "We further evaluated the relationship between the rate of insulin-stimulated carbohydrate oxidation and the risk of developing type 2 diabetes in 287 full-heritage Pima Indians." (PMID 24728127, 2014). "Studies have shown an independent association of low energy-dense foods with lower fasting insulin levels and the metabolic syndrome and a lower risk of type 2 diabetes." (PMID 24510203, 2014). "MicroRNAs (miRNAs) target up to 60% of mammalian mRNAs and have been demonstrated to play a key role in adipocyte differentiation, obesity, insulin sensitivity and risk of developing type 2 diabetes (T2D) in murine models." (PMID 25010252, 2014). "For this reason, insulin is indicated only from second step in the management of type 2 diabetes, when the risk-benefit ratio becomes acceptable." (PMID 24752580, 2014).
type 2 diabetes (continued). "In our study, we found that medication therapy with an insulin agent for type 2 diabetes was associated with a decreased level of HbA1c in all patients and in female patients." (PMID 25202328, 2014). "Glycemic instability is a crucial clinical problem in patients with insulin-deficient (type 1 and advanced type 2) diabetes." (PMID 25393115, 2014). "Amylin is deficient in type 1 diabetes and relatively deficient in insulin requiring type 2 diabetes." (PMID 26237392, 2014). "In patients with type 2 diabetes the type of therapy (diet, oral antidiabetics, insulin) was not related to the risk of osteoporosis in women, while men with insulin therapy had slightly lower BMD values." (PMID 24721668, 2014). "Previous studies on type 2 diabetes have shown an association between exercise capacity and insulin resistance." (PMID 24612649, 2014). "Type 2 diabetes is characterized by chronic hyperglycemia caused by an impaired function and survival of insulin producing pancreatic beta cells and an insulin resistance of peripheral tissues." (PMID 24642635, 2014). "Genetic predisposition for type 2 diabetes is associated with impaired insulin sensitivity, adipocyte hypertrophy and other markers of adipose tissue dysfunction." (PMID 25148116, 2014). "Abnormally high blood glucose levels in type 2 diabetes are caused by relative insulin insufficiency, impaired insulin secretion due to beta cell dysfunction, and impaired glucose tolerance." (PMID 25053966, 2014). "Obesity causes an insulin-resistant state in target tissues and is a high risk factor for chronic diseases such as type 2 diabetes." (PMID 25053966, 2014). "After adjusting for age, gender, body mass index percentiles, and fasting plasma insulin, the E23K polymorphism contributed to an increased risk for type 2 diabetes (P = 0.047)." (PMID 25309595, 2014). "Gene variants in other mitochondrial transcription factors, namely TFB1M, have been found to correlate with reduced insulin secretion, elevated postprandial glucose levels and increased risk of developing type 2 diabetes." (PMID 25532126, 2014). "Type 1 diabetes results from autoimmune destruction of insulin producing β-pancreatic cells, whereas type 2 diabetes involves loss of glucose stimulated insulin secretion and a gradual diminution of β-cell mass." (PMID 24739928, 2014). "Type 2 diabetes arises when beta cells produce insufficient insulin to meet the increased hormone demand, caused by insulin resistance." (PMID 25610877, 2014). "This putative insulin/PI3K-AKT signaling pathway suggested that functional loss of Cmah gene during human evolution is closely associated with Type II diabetes due to altered miRNAs and target genes interaction." (PMID 25243123, 2014). "Adipose tissue differentiation and function is related to insulin sensitivity and other characteristic metabolic changes associated with type 2 diabetes." (PMID 25148116, 2014). "Other explanations for the association between insulin use and fracture include increased duration of type 2 diabetes, and the inclusion of individuals with type 1 diabetes." (PMID 24919660, 2014). "SNP rs3828329 on 2p25.3 in the ACP1 gene is has been shown to be significantly associated with fasting insulin and insulin sensitivity in type 2 diabetes in Mexican-Americans." (PMID 25123136, 2014). "In this meta-analysis, we conducted a rigorous search of all available published cohort studies to quantify the possible association between insulin use and incidental DR in individuals with type 2 diabetes." (PMID 24972631, 2014). "One of the novel characteristics of this study is the use of liver tissue biopsied from the same individual before and after significant weight loss and improvement in insulin sensitivity and/or remission of type 2 diabetes." (PMID 25539584, 2014).
type 2 diabetes (continued). "We have previously demonstrated that the NEAT score determined by our original questionnaire is favorably associated with insulin sensitivity, abdominal obesity, lipid metabolism and blood pressure in patients with type 2 diabetes." (PMID 25075310, 2014). "Type 2 diabetes, a heterogeneous disorder with hyperglycaemia caused by impaired insulin secretion and decreased insulin sensitivity is characterized by aberrant expression of several important proteins in β-cells and pancreatic islets." (PMID 25988147, 2014). "The higher proportion of saturated fatty acids in serum lipids or phospholipids in muscles associated with higher fasting insulin levels would reduce insulin sensitivity and increase the risk of type 2 diabetes." (PMID 24971303, 2014). "Alteration in melatonin level has also been shown to affect insulin sensitivity, and recent studies in humans suggest that a low melatonin level is a risk factor for type 2 diabetes." (PMID 24694994, 2014). "In unadjusted Cox regression models all tissue-specific IR indices and fasting plasma insulin levels significantly predicted an increased risk of incident type 2 diabetes and incident CVD events." (PMID 25310839, 2014). "For example, decreased insulin-stimulated GLUT4 translocation in skeletal muscle is a hallmark of IR associated with type 2 diabetes in humans and rodents." (PMID 24977043, 2014). "Metformin lowers elevated insulin levels associated with type 2 diabetes by inhibiting hepatic gluconeogenesis via AMP-activated protein kinase (AMPK) activation." (PMID 24858012, 2014). "The key example for the loss of phenotypic flexibility is the development of type 2 diabetes with the impaired response to insulin secretion." (PMID 25106484, 2014). "In keeping with this finding, apoAI as a component of rHDLs has also been shown to reduce plasma glucose levels in patients with type 2 diabetes, associated with an rHDL-mediated increase in plasma insulin." (PMID 24347528, 2014). "Further, physicians see hypoglycaemia as a limiting factor in how aggressively they can use therapies such as insulin (associated with hypoglycaemia) to treat type 2 diabetes (T2D)." (PMID 24351086, 2013). "Reduced expression of the transcription factor, prospero homeobox 1 (Prox1), by cis-regulatory variants altered beta cell insulin secretion which conferred susceptibility to type 2 diabetes." (PMID 23542897, 2013). "Impaired insulin signaling is a key feature of type 2 diabetes and is associated with increased ubiquitin-proteasome-dependent protein degradation in skeletal muscle." (PMID 23437325, 2013). "A cure for type 1 diabetes and some cases of type 2 diabetes would require the means to replace the functions of deficient insulin-secreting β-cells to regulate abnormal levels of blood glucose." (PMID 23874448, 2013). "IFG identifies a high-risk group of people who are more insulin resistant and have an elevated risk for progression into type 2 diabetes and CVD." (PMID 23533799, 2013). "The aim of the present study was to use the UCPCR to test for absolute insulin deficiency in older people with insulin‐treated Type 2 diabetes." (PMID 23659458, 2013). "The aim of this study is to investigate the prevalence and determine the possible risk factors of poor sleep quality in Chinese type 2 diabetes patients with insulin treatment." (PMID 23383010, 2013). "While provider attitudes and aspects of the health system are likely to be implicated, a reluctance to start insulin therapy has been shown to occur in at least one-quarter of insulin-naïve people with type 2 diabetes." (PMID 24223860, 2013). "Type 2 diabetes which is much more prevalent (90%) is caused by a combination of resistance to insulin action and an inadequate compensatory insulin secretory response." (PMID 23587270, 2013). "We have documented that HCTZ therapy leads to the development of hepatic steatosis and compromised insulin sensitivity in subjects at high risk for type 2 diabetes." (PMID 23837919, 2013).